INS (insulin)
Diseases named in the same sentence as INS in open-access papers (continued):
Sharing a sentence is not in itself a finding about the gene and the disease.
Insulin resistance (continued). "T2DM is a heterogeneous, progressive metabolic condition defined by tissue insulin resistance, insufficient compensatory insulin production, and faulty insulin secretion by pancreatic beta-cells." (PMID 37109541, 2023). "This is relevant to metabolic disease in humans because adipose insulin resistance is an early event in the path to type 2 diabetes, and disrupting insulin-stimulated glucose uptake in adipocytes compromises whole-body glucose homeostasis." (PMID 36808134, 2023). "Impaired tissue sensitivity to insulin or insulin resistance (IR) paradoxically leads to diseases with an inflammatory component despite hyperinsulinemia." (PMID 37372966, 2023). "Weight, body mass index (BMI), fasting insulin levels and homoeostatic model assessment for insulin resistance (HOMA-IR) were higher in hyperandrogenic compared with normo-androgenic participants (p=0.034, p=0.015, p=0.029 and p=0.034, respectively)." (PMID 37989369, 2023). "Obesity-related insulin resistance (IR) is a well-known hallmark of early NAFLD progression, yet the mechanism linking aberrant insulin signaling to hepatocyte inflammation has remained unclear." (PMID 37408268, 2023). "Herein, we start by reviewing the signal transduction pathways of insulin action on glucose uptake, as well as the mechanisms by which sphingolipids can interfere with the process and induce insulin resistance." (PMID 37762318, 2023). "Reduced pik3r1 is sufficient to ameliorate high-fat diet-induced insulin resistance, enhance insulin signaling in white adipose tissues and skeletal muscle, and also improve whole-body insulin sensitivity." (PMID 38317714, 2023). "As expected, our metabolic study showed that while MetS elevated serum insulin levels and promoted insulin resistance, the presence of periodontitis further contributed to hyperinsulinemia and to enhanced insulin resistance." (PMID 37176029, 2023). "The homeostasis model assessment of insulin resistance (HOMA-IR) and the quantitative insulin sensitivity check index (QUICKI) equation were used to estimate insulin resistance and insulin sensitivity, respectively." (PMID 38063544, 2023). "Similar findings were confirmed by other studies, however, some studies reported higher levels of AMH in PCOS women with insulin resistance, compared with those with normal insulin sensitivity." (PMID 37034292, 2023). "The relative TAG decreases in the liver of fed KD mice indicate insulin resistance, the increase in the glucagon/insulin ratio, and/or the increase in RA." (PMID 37011860, 2023). "Ultimately, traditional therapy methods for T2DM, such as insulin sensitizers and secretagogues, have effectively addressed the intricate interaction between insulin resistance and decreased insulin secretion." (PMID 38283440, 2023). "Conversely, increased circulating FFA impairs insulin cellular action to further contribute to insulin resistance via a feed-forward mechanism." (PMID 39434962, 2023). "Type 2 diabetes mellitus (T2DM) is a chronic disease characterized by a state of hyperglycemia, which derives from impaired insulin secretion by pancreatic islet β-cells and insulin resistance." (PMID 38140319, 2023). "Insulin resistance was casused by Serine phosphorylation of IRS substrates by jun N-terminal kinase (JNK1), and inhibitor of NF-κB-kinase β (IKKβ, an NF-κB-activating kinase) Decreased insulin secretion and insulin resistance leads to hyperglycemia." (PMID 37507664, 2023). "In our regression analysis between CT-based adiposity indices and insulin resistance, all adiposity indices were associated with HOMA-IR and Matsuda insulin sensitivity index in univariate analyses." (PMID 37864066, 2023). "Insulin resistance in various insulin-target organs, including the liver, muscle, and adipocytes, and pancreatic cell failure are frequent characteristics of type 2 diabetes." (PMID 37954695, 2023).
Insulin resistance (continued). "As a result, a dysfunctional adipocyte ends up by presenting an altered glucose metabolism due to a defective insulin pathway, a condition known as insulin resistance." (PMID 37242297, 2023). "This is consistent with our literature review, which found that it becomes difficult to control blood glucose with increasing age because the insulin secretion of pancreatic beta cells is reduced and insulin resistance increases." (PMID 37987427, 2023). "The effects of grip strength and ALM on type 2 diabetes, NAFLD, hypertension, CHD, and MI were partly attenuated after adjusting for insulin resistance (fasting insulin)." (PMID 37403750, 2023). "Vrel, and A were both moderately correlated with the baseline insulin concentration, insulin resistance (RHOMA), insulin sensitivity (SHOMA), and glucose disposition (DHOMA) derived from the homeostatic model assessment." (PMID 36771243, 2023). "Within both groups, there were decreases in fasting plasma glucose, insulin, C-peptide, insulin resistance and percent β-cell function." (PMID 38068805, 2023). "Type 2 diabetes mellitus (DM2) is a manifestation of insulin resistance, which demonstrates itself through a faulty response to insulin and subsequent altered glucose metabolism." (PMID 38003403, 2023). "The insulin resistance present in type 2 diabetes along with the accompanying high insulin levels increase the synthesis of IGF-1." (PMID 37373398, 2023). "In type 2 diabetes, hyperglycemia is the result of inadequate production of insulin and inability of the body to respond fully to insulin which is called as insulin resistance." (PMID 37240813, 2023). "The modulation of the insulin signaling pathway and improved balance between proinflammatory, and anti-inflammatory cytokines contribute to reducing insulin resistance in prediabetic rats." (PMID 37324274, 2023). "As excessive amounts of insulin levels directly increase ovarian production of androgens, hyperinsulinemia and insulin resistance are considered as the pathogenesis factors of PCOS." (PMID 37559131, 2023). "In contrast, ApoM was shown to promote insulin secretion and antagonize insulin resistance after activating S1PR1 and/or S1PR3 signaling." (PMID 37867511, 2023). "Periodontal therapy can improve the periodontal status, reduce insulin resistance, and improve insulin sensitivity." (PMID 37629193, 2023). "In this sense, insulin antibodies (IAs) have been identified in diabetic patients for regular insulin treatments, and are associated with exogenous insulin antibody syndrome (EIAS) that is characterized by insulin resistance with hyperglycemia or hypoglycemia." (PMID 38105750, 2023). "Insulin resistance can develop as early as the second trimester, and by the third trimester and is enhanced by around 56% in patients due to impaired insulin signaling in skeletal muscle and adipose tissue." (PMID 36631877, 2023). "Insulin resistance (IR) is defined as “a condition in which insulin sensitivity in tissues is reduced and insulin action is inadequate”." (PMID 38004118, 2023). "In insulin resistance, this pathway is disrupted, and insulin triggers the MAPK pathway, which promotes renal vasoconstriction." (PMID 37760906, 2023). "In contrast, individuals with IFG experience severe hepatic insulin resistance while maintaining normal or near-normal muscle insulin sensitivity." (PMID 38115080, 2023). "PEG as monotherapy has been proven to increase insulin sensitivity through the block of GH action at the receptor level and its consequent effect on insulin resistance and also to exert a positive impact on peripheral insulin sensitivity." (PMID 36892739, 2023). "In this study, both the combination group and the selenium-only group experienced a significant improvement in markers of inflammation (hs-CRP), oxidative stress (glutathione), and insulin resistance (insulin, HOMA-IR, and QUICKI)." (PMID 36984879, 2023).
Insulin resistance (continued). "Metformin is considered as an insulin-sensitizer by virtue of its capability to reduce insulin resistance and decrease plasma fasting insulin levels." (PMID 37631325, 2023). "Under conditions of insulin resistance, β-cells are stimulated to secrete more insulin than under conditions of normal insulin sensitivity." (PMID 36996012, 2023). "In T2DM, serum 12,13-diHOME was positively correlated with C-peptide, fasting insulin, and evaluation of the homeostasis model of insulin resistance (HOMA-IR) and was negatively correlated with HbA1c." (PMID 37386486, 2023). "Insulin resistance (IR) is a pathological condition of impaired biological response of tissues to insulin, despite normal or elevated insulin concentration in the blood." (PMID 37373131, 2023). "The outcome indicators include 25-hydroxyvitamin D [25(OH)D] levels, insulin resistance index (homeostasis model assessment of insulin resistance), fasting blood glucose, and fasting insulin levels (FINS)." (PMID 37861495, 2023). "Due to obesity-induced prediabetes, the attenuation of weight gain by probiotics reduced the severity of glucose intolerance and insulin resistance, as indicated by several markers (fasting blood glucose, fructose, insulin with OGTT, and HOMA score)." (PMID 36986190, 2023). "Fasting insulin was also measured in six studies and used to calculate insulin resistance using the homeostasis model assessment of insulin resistance (HOMA-IR) formula." (PMID 37375611, 2023). "Resting adenosine triphosphate (ATP) synthesis in skeletal muscle in insulin-resistant subjects is reduced compared with insulin-sensitive individuals, suggesting a contribution of mitochondrial dysfunction to insulin resistance." (PMID 37998725, 2023). "Obesity-related infiltration of immune cells, inflammation, and increased oxidative stress promoted metabolic damage in insulin-sensitive tissues, ultimately leading to insulin resistance, organ failure, and premature aging." (PMID 36766593, 2023). "The pathogenesis of AN with obesity can be explained on the basis of secondary insulin resistance, where the target cells fail to respond to normal levels of circulating insulin, resulting in compensatory hyperinsulinemia." (PMID 36964104, 2023). "The emergence of insulin resistance, as a harbinger of heightened insulin requisites and, ultimately, beta-cell dysfunction, underscores the critical significance of identifying markers of this complex metabolic derangement." (PMID 38105338, 2023). "Cortisol, a glucocorticoid that raises blood sugar and reduces insulin secretion, has been shown in a clinical study to increase insulin resistance in patients with T2D when the HPA axis loses its ability to lower cortisol levels during hyperglycemia." (PMID 36936164, 2023). "Increased levels of insulin and its precursors (proinsulin and its split products) during insulin resistance improved the expression of PAI‐1, and this change was also observed in patients with type 2 diabetes." (PMID 37314019, 2023). "As a consequence, Khk knockdown had no apparent effect on body weight, water intake, serum glucose, serum fructose, serum sorbitol, fasting glucose, fasting insulin, or homeostatic model assessment of insulin resistance (HOMA-IR)." (PMID 37907746, 2023). "Individuals with IGT exhibit substantial muscle insulin resistance, along with relatively modest hepatic insulin resistance and decreased late-phase insulin production." (PMID 38115080, 2023). "This drop in plasma TG in the vitamin K4 group can be clarified by the decrease in fasting serum insulin and the improvement of insulin resistance as assessed by HOMA-IR by around 50% in the same group." (PMID 37552330, 2023). "Fasting insulin and HOMA-IR were decreased as expected, and serum valine was strongly associated with insulin resistance." (PMID 37049555, 2023).
Insulin resistance (continued). "Insulin resistance occurs when the increased amount of insulin produced and put into circulation cannot meet the metabolic needs of peripheral tissue." (PMID 36751233, 2023). "The AHW group showed less immunoreactivity to insulin than the DC group, indicating that AH can prevent hyperglycemia induced by blunting β-cell overcompensation and insulin resistance in type 2 diabetic mice." (PMID 37895834, 2023). "Insulin resistance is an impaired biological response to physiological insulin levels in tissues such as the liver, muscles, and adipocytes." (PMID 37121975, 2023). "Changes in the liver and muscles have long been recognized as major contributors to systemic insulin resistance occurrence, as fat accumulation in the liver is a major factor in reduced hepatic insulin sensitivity, resulting in fasting hyperglycemia." (PMID 37298118, 2023). "Indices of insulin sensitivity/ insulin resistance depicted different characteristics with wild type and heterozygousvariant of PPARγ2 gene." (PMID 37928491, 2023). "On the other hand, an excess of circulating insulin levels will promote hyperinsulinemia, and, as a consequence, systemic insulin resistance, a key feature of type 2 diabetes." (PMID 35457000, 2022). "Insulin resistance in peripheral target tissues, as well as reduced insulin secretory capacity of pancreatic β-cells, play a role in the development of type 2 diabetes." (PMID 35268696, 2022). "There was a greater decrease in body weight, BMI, fasting plasma glucose, insulin concentration, and insulin resistance index (HOMA-IR) in the synbiotic group compared to the placebo group." (PMID 36013992, 2022). "Our clinical data showed that PCOS group fasting insulin levels are within the normal range, but higher than the HC group, suggesting 1-Linoleoylglycerophosphocholine concentration can predict the rise of insulin resistance." (PMID 36564416, 2022). "Chronic hyperglycemia reduces the antioxidant capacity of CAT, SOD, GPx, and erythrocyte glutathione (GSH), provoking insulin resistance through the inhibition of insulin signals." (PMID 36080407, 2022). "As insulin is the main regulator of carbohydrate and fat metabolism, impairment of its function leads to insulin resistance." (PMID 36819480, 2022). "For example, some patients exhibit strong insulin resistance and weak insulin secretion function despite metformin treatment." (PMID 36704100, 2022). "The subsequent increase in these ROS associated with the hyperglycemic diabetic state leads to decreased insulin gene expression and secretion, deteriorates cellular function, increases insulin resistance, and can ultimately lead to apoptosis." (PMID 35498435, 2022). "In obese individuals, insulin resistance promotes muscle catabolism because insulin is a powerful anabolic signal." (PMID 35100595, 2022). "Impaired insulin secretion and increased insulin resistance (IR) [or decreased insulin sensitivity (IS)] play a major role in the pathogenesis of DM." (PMID 36137169, 2022). "Dysregulation of this protein induces mitochondrial dysfunction, which interferes with insulin uptake in the brain, resulting in insulin resistance." (PMID 36092798, 2022). "Meanwhile, the levels of glucose, insulin, and homeostatic model assessment of insulin resistance (HOMA‐IR) were significantly increased, suggesting hyperinsulinemia and insulin resistance." (PMID 35072981, 2022). "The score of HOMA-IR to determine the insulin resistance showed the highest score in DC group as compared to HC and test groups, thus reduced sensitivity of insulin was observed in DC group." (PMID 36302045, 2022). "T2DM occurs because of a combined impairment in insulin secretion (β cell failure) and insulin action (insulin resistance)." (PMID 35499716, 2022). "Insulin resistance or impaired insulin-mediated regulation of glucose metabolism results in elevated plasma insulin concentration that is a crucial abnormality in patients with metabolic syndrome." (PMID 35033025, 2022).
Insulin resistance (continued). "Extreme values for the archetype C score (n = 84) were associated with insulin resistance (low 2 h oral glucose insulin sensitivity [2hOGIS], Stumvoll, and Matsuda indices, as well as high fasting and mixed-meal tolerance test [MMTT] insulin levels)." (PMID 35106505, 2022). "RBP4 is involved in the regulation of insulin and insulin resistance, which would affect fetal growth." (PMID 35505881, 2022). "Insulin resistance represents a partial disruption of communication between these tissues, in which target tissues of insulin become resistant to insulin signaling despite initial compensation by the pancreas." (PMID 35625904, 2022). "Early and/or increased risks of insulin resistance underlie several major neurodevelopmental disorders (NDD), with decreased CNS responsiveness to insulin contributing to developmental delays and cognitive impairments." (PMID 36429060, 2022). "Early in disease progression, insulin resistance impacts the peripheral tissues (muscle, liver and adipose tissue), promoting them to become resistant to circulating peripheral insulin." (PMID 36555450, 2022). "In a study that included 42 adolescents, supplementation of GSE (100 mg/day) for 8 weeks significantly reduced insulin levels and insulin resistance (measured by Homeostatic Model Assessment for Insulin Resistance (HOMA-IR))." (PMID 36615843, 2022). "Insulin resistance refers to a condition in which insulin-sensitive cells have a subnormal response to physiological concentrations of insulin." (PMID 35327570, 2022). "Calorie restriction and low protein diets reduced insulin resistance and increased insulin sensitivity that stimulated more lipid synthesis." (PMID 35257470, 2022). "Proia’s group reported that these mice display enhanced phosphorylation of InsR in skeletal muscle following insulin injection, enhanced glucose and insulin tolerance, and reduced susceptibility to high-fat diet (HFD)-induced insulin resistance." (PMID 35628171, 2022). "The Iraqi group in our study had higher beta-cell function assessed by HOMA-β, suggesting early compensatory insulin secretion for the higher insulin resistance." (PMID 36309585, 2022). "Hepatic insulin resistance refers to impaired sup-pression of glucose production by insulin in hepatocytes." (PMID 35885586, 2022). "Analyses in 16,113 Chinese adults reveal that Mut-Reg1cp individuals had higher incidence of T2D and presented impaired insulin secretion as well as increased insulin resistance." (PMID 36302749, 2022). "Insulin resistance impairs glucose removal, resulting in a compensatory increase in beta-cell insulin production and hyperinsulinemia." (PMID 35455055, 2022). "The relationship between EETs and insulin resistance (IR) shows that EETs can stimulate insulin secretion of islet cells, improve glucose homeostasis, inhibit apoptosis of islet cells, and play a role in regulating blood glucose." (PMID 35431942, 2022). "Using HOMA-IR to assess insulin resistance, we found that insulin sensitivity was similar at all ages 10–28 months of age." (PMID 36315375, 2022). "Incretin peptides are of great importance in glucose homeostasis as they increase insulin secretion by β-cells, reduce insulin resistance, inhibit β-cell apoptosis, and stimulate β-cell proliferation." (PMID 36077491, 2022). "In this study, OZRs served as a model of insulin resistance to understand the altered upstream insulin signaling site, especially at the level of insulin receptors and its substrate in the gastrocnemius muscle." (PMID 36547071, 2022). "Insulin resistance occurs when the pancreas secretes a substantial amount of insulin to maintain glucose levels in the normal range." (PMID 35185617, 2022). "The main reason for developing T2DM is the impaired secretion of insulin by pancreatic β‐cells, generally because of insulin resistance in adipose tissue 1, liver, skeletal muscle, and liver." (PMID 36572938, 2022).